ALB (albumin)
Diseases named in the same sentence as ALB in open-access papers (continued):
Sharing a sentence is not in itself a finding about the gene and the disease.
Hyponatremia (115 papers, 2010 to 2026). An abnormally decreased sodium concentration in the blood. "Hyponatremia was associated with lower BMI, lower nadir BMI, longer disease duration, and an adverse biochemical profile (lower albumin, higher creatinine, higher platelet counts, and higher bicarbonate levels)." (PMID 42290991, 2026). "Ultimately, only increasing ALP levels, decreasing albumin, and hyponatremia development were associated with a shorter OS." (PMID 41375007, 2025). "In multivariable Cox analysis, increasing alkaline phosphatase levels (HR = 1.93, p = 0.009), decreasing albumin (HR = 1.92, p = 0.008) and development of hyponatremia (HR = 1.79, p = 0.033) were associated with a shorter OS." (PMID 41375007, 2025). "Multiple logistic regression analyses identified the albumin level before the oxazolidinone drug therapy as the independent variables associated with the development of hyponatremia." (PMID 36830256, 2023). "In our results, albumin level of pre-administration of oxazolidinone antibiotics was associated with hyponatremia." (PMID 36830256, 2023). "These include poor nutritional status and chronic inflammation as a result of the underlying chronic disease causing hyponatraemia such as infection or malignancy due to interleukin-1 and tumour necrosis factor which decrease hepatic albumin production." (PMID 33299609, 2020). "Other studies have also reported hyponatremia, high creatinine, high bilirubin, and low albumin as risk factors for overt HE." (PMID 33425806, 2020). "Hyponatremia was associated with serum chloride (p = 0.004), albumin (p = 0.002) and SLE disease activity index (SLEDAI) (p = 0.026) in children with SLE." (PMID 27193532, 2016). "Our study further showed that after adjustment for age, WHO stage, CD4 count, hemoglobin and albumin in a multivariate model, severe/moderate hyponatremia remained a high risk factor for death." (PMID 25360785, 2014). "Hyponatremia was also significantly associated with the following biochemical variables: leukocytes above normal, albumin below normal, alkaline phosphatase above normal, and low haemoglobin." (PMID 20145619, 2010). "Hyponatremia was associated with a lower albumin and higher square root CRP levels." (PMID 37744432, 2023). "Also, hyponatremia was reported to be related to a lower level of albumin, which would significantly increase the risk of peritonitis and other infectious diseases." (PMID 33407231, 2021). "Analysis of preoperative laboratory test results showed that high levels of C-reactive protein, leukocytosis, increased urine specific gravity, low hemoglobin, hyponatremia, hypokalemia, low serum protein, and low serum albumin were significant risk factors for postoperative delirium." (PMID 27015177, 2016). "Also, lower eGFR, higher calcium, and lower albumin levels in the serum were significantly associated with hyponatremia in thyroid cancer patients following RAI therapy." (PMID 25170831, 2014). "The 30-day emergency mortality and long-term survival of emergency cancer patients with severe hyponatremia are negatively impacted by lower albumin levels and poor performance status, which indicate worse resistance and more severe disease." (PMID 40422504, 2025). "A decrease in ALB during linezolid therapy is a more selective predictor of hyponatremia than baseline ALB." (PMID 40886330, 2025). "Further prospective analysis of a larger population is needed to confirm our findings that the ECOG score and serum albumin parameters are prognosis markers in cancer patients with severe hyponatremia presenting to the emergency department." (PMID 40422504, 2025). "A lower albumin level and a higher ECOG score are independent risk factors for both 30-day mortality and overall survival of emergency cancer patients with severe hyponatremia." (PMID 40422504, 2025).
Hyponatremia (continued). "Subgroup analysis in patients age ≥ 65 identified the duration of therapy, a history of cardiovascular disease, a history of endocrine diseases, and serum albumin (ALB) decreased during linezolid therapy as key indicators of hyponatremia." (PMID 40886330, 2025). "The selected thresholds for serum albumin, hyponatremia, and hypochloremia were based on the lowest normal reference in our blood biochemistry tests (serum albumin = 40 g/L, hyponatremia NA+ < 137 mmol/L, hypochloremia Cl− < 99 mmol/L)." (PMID 38750370, 2024). "In patients with low albumin levels (albumin < 2.6 g/dL), hyponatremia was happened in approximately 50% in both groups (54.1% and 42.9%)." (PMID 36830256, 2023). "Based on these reports, it was considered that hyponatremia was more likely to occur in the LZD group with low albumin levels than TZD group." (PMID 36830256, 2023). "The analysis suggests that hyponatremia was associated with elevated CRP levels and lower albumin levels, markers of inflammation." (PMID 37744432, 2023). "After adjustment for relevant confounders, hyponatremia remained associated with an increased square root CRP (β = 1.79: 95% CI: 0.22–3.36) and lower albumin levels (β = −0.22: 95% CI: −0.42–−0.01)." (PMID 37744432, 2023). "Compared to patients with normal serum sodium concentrations, patients classified as having hyponatraemia at baseline were on average older, had poorer kidney function, and lower haemoglobin and serum albumin levels." (PMID 37407935, 2023). "We identified albumin levels before the initial oxazolidinone drug treatment and the LZD use of as the independent variables associated with the development of hyponatremia." (PMID 36830256, 2023). "As a result, the patients with high albumin level (albumin ≥ 2.6 g/dL) who used LZD had hyponatremia significantly higher than patients who used TZD (22.6% vs. 0%, p < 0.05)." (PMID 36830256, 2023). "Compared to AECOPD patients with normonatremia, the rate of fever, WBC, NS, NS%, NLR, PCT, ESR, PH, and AG were markedly higher, meanwhile, LYM, EOS, LYM%, EOS%, serum Ca2+, serum Mg2+, and ALB were significantly lower in AECOPD patients with hyponatremia." (PMID 36709254, 2023). "This study revealed that time-averaged serum albumin and creatinine levels in the hyponatremia group were lower than in patients with normonatremia." (PMID 35780279, 2022). "The participants’ opinions regarding the use of albumin in patients with hyponatremia were divergent in question 6C." (PMID 33270161, 2021). "Other inappropriate indications for which albumin was used were hyponatremia, hypervolemia, and respiratory failure." (PMID 34613990, 2021). "Univariate logistic regression analysis revealed that advanced age, longer length of index hospital stay and hyponatremia were positively correlated with the rehospitalization, and albumin level was negatively correlated with the rehospitalization." (PMID 33407231, 2021). "The hyponatremia group had significantly lower serum hemoglobin, calcium, albumin, and cholesterol levels, as well as a shorter follow-up duration and a higher proportion of CCI scores ≥5, than the non-hyponatremia group." (PMID 32891121, 2020). "Serum albumin and protein were significantly lower in the hyponatraemia patients as compared to those with normonatraemia." (PMID 33299609, 2020). "Hyponatremia secondary to salt loss from recurrent malignant ascitic drainage should be managed by the administration of isotonic IVF and/or albumin (154 mEq of sodium in 1 L of 25% albumin)." (PMID 33104204, 2020). "Triglycerides, plasma glucose and cortisol, BNP, total serum protein and albumin were comparable across all three levels of hyponatraemia whereas thyroid-stimulating hormone (TSH) appeared inversely correlated with plasma sodium." (PMID 27770791, 2016). "The serum creatinine and albumin levels were similar among the sodium groups, except for a higher creatinine level in the mild hyponatremia group." (PMID 26732402, 2016).
Hyponatremia (continued). "By expanding plasma volume, albumin infusion suppresses vasopressin release induced by hypovolemia, thereby increasing water diuresis and improvement in hyponatremia." (PMID 26793696, 2015). "Parenteral infusion of albumin is effective in restoring a more physiological circulatory volume and therefore it is useful in patients with severe hyponatremia." (PMID 26237018, 2014). "Hyponatremia and low albumin were more common in the infection group (75.47 and 79.25%, respectively) than in the non-infection group (46.43 and 63.1%, respectively)." (PMID 24137231, 2013). "The proportions of patients with hyperammonemia, increased NEUT numbers, hyponatremia and low albumin were higher in the infection group compared with those in the non-infection group (P<0.05)." (PMID 24137231, 2013). "Alternative therapeutic options for preventing or reversing hyponatremia in neurocritical patients include albumin, fludrocortisone, hypertonic saline, and vasopressin receptor antagonists, such as conivaptan." (PMID 22647340, 2012). "In the continuation group, Grade 1 or 2 treatment‐related adverse events due to any cause included fatigue, pruritus, adrenal insufficiency syndrome, elevated AST/ALT, elevated bilirubin, constipation, albumin reduction, hyponatremia, and increased blood pressure." (PMID 40276064, 2025). "While actively treating hyponatremia, physicians may find that increasing patients’ performance status and administering albumin supplements can improve their prognosis." (PMID 40422504, 2025). "In patients with intestinal necrosis, the WBC (p = 0.034), blood glucose (p = 0.040), Scr (p < 0.001), LDH (p < 0.001), CRP (p < 0.001), and D‐dimer (p < 0.001) levels were higher, the incidence of hyponatremia was higher (p = 0.032), and albumin levels were lower (p = 0.006)." (PMID 41498031, 2025). "However, in multivariate analysis, a decrease of serum albumin during LZD therapy was an independent indicator of hyponatremia." (PMID 40886330, 2025). "Consequently, ALB decrease during LZD therapy predicts hyponatremia more accurately than ALB before LZD therapy." (PMID 40886330, 2025). "Serum biochemical abnormalities included hypoglobulinemia (2.0 g/dl [2.8–5.4]) with a low-normal albumin (2.4 g/dl [2.2–4.6]), hyponatremia (133 mmol/l), hypokalemia (3.1 mmol/l [3.6–4.9]), hypochloremia (101 mmol/l), hypophosphatemia (3 mg/dl [3.2–6.3]), and hypoglycemia (59 mg/dl)." (PMID 38247129, 2024). "Our result revealed the relationship between pre-albumin levels and hyponatremia." (PMID 36830256, 2023). "Yet hyponatremia was associated with a higher serum CRP and lower serum albumin, which may reflect increased state of inflammation." (PMID 37744432, 2023). "There was a significant association between hyponatremia and higher CRP and lower serum albumin levels which may suggest increased inflammation in children with hyponatremia and COVID19/MISC." (PMID 37744432, 2023). "In addition to several of these risk factors, this patient also exhibited laboratory parameters consistent with poor dietary solute and protein intake: hypoosmolar hyponatremia, low serum urea nitrogen, and low serum albumin." (PMID 37255614, 2023). "Hyponatremia in setting of a low serum albumin might have resulted from an ADH dependent free water retention." (PMID 36694746, 2023). "Indirect potentiometry measurements are falsely depressed as total protein increases, as seen in our study with albumin, which could have resulted in an overdiagnosis of hyponatremia." (PMID 37744432, 2023). "Therefore, cases that LZD is administered by injection should be used more carefully with hyponatremia in patients with low albumin level." (PMID 36830256, 2023). "Furthermore, in patients with low albumin levels (albumin < 2.6 g/dL), approximately 50% hyponatremia was observed in both groups, and monitoring sodium level is required." (PMID 36830256, 2023).
Hyponatremia (continued). "Human albumin (HA), which has been recommended to manage hepatorenal syndrome, spontaneous bacterial peritonitis, and large volume paracentesis, seems to be effective for the management of hyponatremia." (PMID 36614908, 2022). "The higher serum albumin in MS-CKD could be due to higher protein-calorie intakes and/or a hypovolemic state associated with hypotonic hyponatremia." (PMID 34067952, 2021). "In our study, those with hyponatraemia had significantly lower serum albumin as compared to those with normonatraemia (31.6 ± 16.5 vs. 36.1 ± 22.4; p < 0.001) and may have accounted independently to increase the mortality in the hyponatraemia arm of the study." (PMID 33299609, 2020). "The prevalence of hyponatremia in the emergency department (ED) is reported to range from 2.3–44%, while prevalence of hypernatremia is 1.1–4.4%, hypokalemia 10.2–39%, hyperkalemia 0.8–13%, and albumin-corrected hypercalcemia 0.7–7.5%." (PMID 31022222, 2019). "In Caraceni’s study, albumin infusion significantly reduced the incidence of hyponatremia." (PMID 31596729, 2019). "Hypovolemia was ruled out as the cause of the hyponatremia with a 48-h albumin challenge (25 g IV q6 h)." (PMID 28352627, 2017). "Volume expansion with 48 h of albumin challenge was conducted to rule out hyponatremia caused by hypovolemia, which often is the case given the frequent combination of lactulose and diuretic therapy in cirrhotic patients." (PMID 28352627, 2017). "However, any final recommendation regarding the exact dosage of albumin will require prospective, randomized control trials incorporating serum renin as an outcome parameter along with renal impairment and hyponatremia." (PMID 26150850, 2015). "In uremic patients with PDRP, hyponatremia at admission associated with a high frequency of gram negative bacilli infection, low serum albumin and phosphate levels, low SGA score, and poor prognosis with long hospital stay and high mortality rate." (PMID 25012614, 2014). "After adjusting for sex, age, WHO stage, CD4 count, hemoglobin and albumin, the relative hazard was 3.5 (95% CI: 1.9–6.5) for patients with moderate/severe hyponatremia (P<0.001), and 1.5 (95% CI: 0.9–2.4) for those with mild hyponatremia (P = 0.161), compared with normonatremic patients." (PMID 25360785, 2014). "However, given the low albumin concentration of our critically ill patients, it is conceivable that the net sodium-retaining effect is reduced as compared with patients with normal protein concentration, contributing to the observed hyponatremia." (PMID 39437128, 2025). "Therefore, we analyzed the incidence of hyponatremia by renal function and albumin level." (PMID 36830256, 2023). "Further Cox regression also could not reveal that serum albumin had a significant effect on the risk association between hyponatremia and all-cause mortality or new MACE in model." (PMID 35780279, 2022). "The results of the survival analysis showed that the serum albumin level and ECOG score of cancer patients significantly affected the emergency mortality of patients with severe hyponatremia." (PMID 40422504, 2025). "Considering ALB change during LZD therapy, a significant positive correlation was detected between the decrease in serum albumin during LZD therapy and hyponatremia." (PMID 40886330, 2025). "Duration of therapy, eGFR, serum albumin decreases during LZD therapy, previous cardiovascular disease and previous endocrine diseases were identified as indicators of hyponatremia." (PMID 40886330, 2025). "Severe hyponatremia patients with a high ECOG score and/or a low albumin level should be monitored and followed more closely." (PMID 40422504, 2025). "Our results showed that baseline C‐reactive protein/albumin ratio, neutrophil/lymphocyte ratio, NSE level, hyponatremia, the efficacy of first‐line chemotherapy, and stage were independent prognostic factors for both OS and PFS in SCLC." (PMID 37015898, 2023).
Hyponatremia (continued). "PICU patients had higher prevalence of hyponatremia, elevated admission CRP levels, and elevated D-dimer; they also had lower albumin, potassium, calcium, sodium, and platelet count." (PMID 37744432, 2023). "Then, 8 g/L of albumin per liter of ascites liquid should be administered in order to avoid AKI, hyponatremia, or HE." (PMID 36676081, 2023). "Conversely, hyper-hypo-natremia subjects exhibited lower levels of serum magnesium (Mg, mmol/L), carbon dioxide-binding capacity (CO2-CP, mmol/L), albumin/globulin ratio (A/G), serum iron (Fe, umol/L), and hemoglobin (HGB, g/L) (P < 0.05)." (PMID 37663278, 2023). "Although albumin infusion reduced the incidence of post-paracentesis circulatory dysfunction and hyponatremia, it did not affect overall mortality or renal impairment in cirrhotic patients undergoing LVP." (PMID 38139434, 2023). "Removal of less than 5 L does not appear to have significant hemodynamic consequences (A1), however, in patients with hemodynamic instability (systolic blood pressure < 90 mm Hg), hyponatremia < 130 mmol/L and/or presence of AKI, albumin infusion should be strongly considered for paracentesis < 5 L." (PMID 37358642, 2023). "Of the established laboratory markers, albumin, alkaline phosphatase and hyponatremia but not lactate dehydrogenase (LDH) significantly predicted OS." (PMID 35681605, 2022). "Hyponatremia following TBI can be due to syndrome of inappropriate ADH secretion (SIADH) or cerebral salt wasting syndrome, but it can also be due to decreased serum albumin following acute phase response." (PMID 34595082, 2021). "CVD, eGFR, albumin, HbA1c and BMI showed positive correlation with hyponatremia in diuretic non-users." (PMID 27841359, 2016). "Other approaches, such as albumin infusion and the use of vaptans—which act by specifically antagonizing the effects of AVP on the V2 receptors located in the kidney tubules—have been evaluated for their role in the management of hyponatraemia." (PMID 24760233, 2014). "In both univariate analysis and multivariate analysis, ALB level was not related to hyponatremia." (PMID 40886330, 2025). "Prior studies demonstrated that LVP without albumin substitution leads to AKI or hyponatremia." (PMID 37410459, 2023). "In euvolemic patients, selected laboratory tests (e.g., measured serum osmolality, serum glucose, lipid profile, and total protein albumin gap) will help to rapidly rule out hypertonic or isotonic hyponatremia and the remaining patients are likely to have hypotonic hyponatremia." (PMID 37007374, 2023). "Patients whose hyponatremia failed to improve with albumin challenge were started on midodrine and octreotide at 10 mg po tid and 100 μg sq tid, respectively, with rapid up-titration as tolerated to respective maximal doses of 15 mg tid and 200 μg tid within the first 24 h." (PMID 28352627, 2017).